CCDC117 (coiled-coil domain containing 117)
Description:
Facilitates DNA repair, cell cycle progression, and cell proliferation through its interaction with CIAO2B.
Synonyms: FLJ33814; dJ366L4.1
Tractability: PROTAC: ubiquitination databases record sites on it.
Gene: Protein-coding gene on chromosome 22 (28,772,674 to 28,789,301, forward strand). Ensembl gene ENSG00000159873.
Subcellular location: Cytoplasm, cytoskeleton, spindle; Nucleus
Subcellular location (Human Protein Atlas): Nucleoplasm; Cytosol; Microtubules
Gene Ontology:
Molecular function: protein binding
Biological process: positive regulation of cell population proliferation; positive regulation of DNA repair
Cellular component: mitotic spindle; nucleus; spindle
Genetic constraint (gnomAD): Loss-of-function variants: 1 observed, 18.7 expected, observed/expected ratio (o/e) 0.0535, 90% interval 0.018 to 0.25. The upper end of that interval is the gene's LOEUF score, 0.25, which puts it in group 1 of 6, group 1 being the genes least tolerant of losing a copy. Missense variants: 372 observed, 320.27 expected, observed/expected ratio (o/e) 1.16, 90% interval 1.07 to 1.27. Synonymous variants: 130 observed, 113.84 expected, observed/expected ratio (o/e) 1.14, 90% interval 0.99 to 1.32.
Homologues: Orthologues: chimpanzee CCDC117 (97% identical), macaque CCDC117 (95% identical), pig CCDC117 (90% identical), dog CCDC117 (89% identical), guinea pig CCDC117 (83% identical), mouse Ccdc117 (78% identical), rat Ccdc117 (71% identical), rabbit CCDC117 (70% identical), tropical clawed frog ccdc117 (33% identical), zebrafish ccdc117 (20% identical).
Diseases named in the same sentence as CCDC117 in open-access papers:
CCDC117 is named in the same sentence as 2 diseases in open-access papers, as found by Europe PMC text mining. Sharing a sentence is not in itself a finding about the gene and the disease. The quoted sentences say what the papers report.
cancer (2 papers, 2015 to 2021). A tumor composed of atypical neoplastic, often pleomorphic cells that invade other tissues. "However, both Ccdc117 and ACY1 primarily appear to play a role in cancers, which are a group of diseases that are mechanistically different from vascular disease." (PMID 33760887, 2021).
CCDC117 also shares sentences with these, for which no sentence is quoted: esophageal squamous cell carcinoma (1 paper).